TFAP2A (transcription factor AP-2 alpha)
Diseases named in the same sentence as TFAP2A in open-access papers (continued):
Sharing a sentence is not in itself a finding about the gene and the disease.
lung adenocarcinoma (14 papers, 2020 to 2026). A carcinoma that arises from the lung and is characterized by the presence of malignant glandular epithelial cells. "Analysis of lung adenocarcinoma and lung squamous cell carcinoma cohorts from the TCGA public database revealed that TFAP2A is significantly overexpressed in tumor tissues, consistent with our experimental findings." (PMID 41438579, 2026). "For example, TFAP2A enhances the metastatic ability of lung adenocarcinoma through the miR-16/TFAP2A/PSG9/TGF-β axis and promotes the progression of lung adenocarcinoma through epithelial–mesenchymal transition (EMT) by inducing the expression of KRT16." (PMID 39695171, 2024). "TFAP2A induced Keratin-16 overexpression, promotes tumorigenicity in lung adenocarcinoma and metastasis via epithelial-mesenchymal transition (EMT)." (PMID 36123698, 2022). "In recent years, TFAP2A has been proved to promote the proliferation and metastasis of lung adenocarcinoma, cervical cancer, and other cancer cells, mainly by affecting EMT to promote tumor metastasis." (PMID 36284637, 2022). "In addition, the mRNA level of PSG9 significantly increased with an increase in the transcription factor AP-2α (TFAP2A) in lung adenocarcinoma, which predicts poorer OS and PFS, probably because of the promotion of tumor metastasis." (PMID 36276966, 2022). "Studies have shown that transcription factor AP-2 alpha (TFAP2α) promotes the proliferation, invasion, and metastasis of lung adenocarcinoma cells through ITPKA overexpression, which is induced by an interaction with Drebrin 1 (associated with cancer metastasis) and activation of EMT." (PMID 33988228, 2021). "TFAP2A is the upstream transcription factor of ITPKA, which promotes the occurrence and development of lung adenocarcinoma (LUAD) by interacting with Drebrin1." (PMID 37208656, 2023). "TFAP2A and TJP1 have both been identified in the lymph node of lung adenocarcinoma as potential biomarkers." (PMID 34575089, 2021). "Moreover, miRNA-16 is involved in pulmonary tumorigenesis, particularly in lung adenocarcinoma, where transcription factor AP-2α (TFAP2A) has been shown to be overexpressed and to induce EMT via miR-NA-16 family/TFAP2A/PSG9/TGF-β." (PMID 37190223, 2023).
bladder cancer (13 papers, 2016 to 2025). "TFAP2A is the most common gene mutation in bladder cancer patients (5%), and most of the alterations were amplification (4.17%)." (PMID 37859819, 2023). "We next performed correlation analysis and found that TFAP2A was upregulated in bladder cancer tissues and positively associated with lncRNA BCCE4." (PMID 37705121, 2023). "However, while the role of the Transcription Factor AP-2 Gamma (TFAP2C) gene (encoding AP-2γ) in bladder cancer and various other cancer types currently appears unequivocal, the role(s) of the TFAP2A gene (encoding AP-2α) is uncertain." (PMID 33718178, 2021). "WWOX and TFAP2A demonstrate tumor suppressor synergism in high-grade bladder cancer, similar to intermediate grade." (PMID 37859819, 2023). "In bladder cancer, in cooperation with PPARɣ inactivation and other transcription factors, TFAP2A and TFAP2C overexpression induced the shift from the luminal subtype to the basal-squamous transition during tumor progression." (PMID 37291585, 2023). "In human bladder cancer cells, TFAP2A was established to be positively correlated with TP63, and it positively regulated TP63 expressions." (PMID 35494004, 2022). "Using a combination of the two drugs, several proteins associated with the basal subtype of bladder cancers were consistently decreased within both cell lines such as KRT1, KRT14, KRT16, P63, and TFAP2A." (PMID 32822399, 2020). "Transcriptional factor TFAP2A and P63 are expressed at high levels in basal bladder cancer and in areas of BC with squamous differentiation." (PMID 32822399, 2020). "TFAP2A was related to worse clinical stage and prognosis in bladder cancer patients." (PMID 40813717, 2025). "Downregulating TFAP2A in bladder cancer cells induces cisplatin resistance." (PMID 37291585, 2023). "Also, the methylation level of TFAP2A was negatively correlated with the clinical stage of bladder cancer." (PMID 37859819, 2023). "However, a combined treatment of TG and PD resulted in a consistent decrease of several proteins associated with the basal subtype of bladder cancers (KRT1, KRT14, KRT16, P63, and TFAP2A)." (PMID 32822399, 2020). "Targetting AP-2 factors could as well lead to drug resistance, as confirmed in pancreatic cancer, where gemcitabine resistance is obtained via TFAP2C suppression by miR-10a-5p, or in bladder cancer where TFAP2A is suppressed by miR-193a-5p." (PMID 30824562, 2019). "Immunohistochemical results from HPA database showed that the expression of TFAP2A, TFAP2B and TFAP2C in clinical samples of bladder cancer patients was higher than that in normal tissues." (PMID 37859819, 2023). "The trend of survival curve of TFAP2A, TFAP2B and TFAP2C in bladder cancer was basically consistent with that of GEPIA." (PMID 37859819, 2023).
branchiooculofacial syndrome (12 papers, 2018 to 2023). "Mutations in the neural crest regulator gene TFAP2A can cause a rare genetic disorder, branchiooculofacial syndrome (BOFS), whose patients have different facial and ocular appearances." (PMID 39872109, 2023).
colorectal cancer (12 papers, 2010 to 2025). A primary or metastatic malignant neoplasm that affects the colon or rectum. "Study in colorectal cancer showed that loss of TFAP2A delayed progression through S-phase into G2-M and decreased phosphorylation of AKT, which were mediated through regulation of TGM2." (PMID 37859819, 2023). "Further, these genes were transcriptionally regulated by TFAP2A, and the high expression of TFAP2A was associated with poor prognosis in colorectal cancer." (PMID 33713277, 2021). "For example, curcumin inhibits colorectal cancer stem cells by activating autophagy via suppressing TFAP2A/ECM pathway." (PMID 39897540, 2025). "A recent study shows that TFAP2A can regulate the function of tumor related macrophages in colorectal cancer." (PMID 37859819, 2023). "TFAP2A overexpression in ovarian and colorectal cancer cells displays epithelioid morphology, possibly because TFAP2A binds to the promoters of E-cadherin and MMP2/9, resulting in increased E-cadherin expression but decreased MMP2/9 levels due to SP1 binding." (PMID 37291585, 2023). "In colorectal cancer cells, TFAP2A inhibits the Wnt/β-catenin signaling pathway." (PMID 37291585, 2023). "For example, TFAP2A could be regarded as a biomarker for predicting the therapy response of PI3K inhibitors in colorectal cancer." (PMID 37291585, 2023). "Intriguingly, in colorectal cancer, TFAP2A could help to establish an inhibitory immune microenvironment by suppressing tumor-associated macrophage (TAM) phagocytosis." (PMID 37291585, 2023). "In colorectal cancer, we found that the cofactors of TFAP2A were PPARG and SP1." (PMID 28684851, 2017). "Polymorphic variants within TFAP2A have also been shown to interact directly with APC and β-catenin preventing β-catenin from associating with TCF4 and thus blocking transcription of WNT-responsive genes in colorectal cancer cells." (PMID 26697505, 2016). "Furthermore, another regulon TFAP2A has also been associated with chemoresistance in colorectal cancer but not yet in TNBC34." (PMID 38472332, 2024). "Recent studies in breast and colorectal cancer demonstrated that inhibition of the SUMO pathway repressed CD44 and cleared the CSC population, mediated through SUMO-unconjugated TFAP2A." (PMID 29383121, 2017). "In colorectal cancer, SIOMICS predicted five shared motifs, which were similar to the motif of the TFs SP1, the CAC-binding protein, TFAP2A (AP-2), KLF6 (GBF), and EGR1 (KROX), respectively (the names in parentheses are the corresponding TRANSFAC TF names)." (PMID 28684851, 2017). "Inhibition of the SUMO pathway in basal breast and colorectal cancers repressed CD44 expression, which was dependent upon TFAP2A." (PMID 29383121, 2017). "Additionally, both TFAP2A and TFAP2C can also bind to the P21 promoter in breast and colorectal cancer cells to enhance P21 expression." (PMID 37291585, 2023). "Indeed, AP-2 family members such as TFAP2A, TFAP2B, and TFAP2C have been shown to be involved in different cancer types such as glioblastoma, melanoma, acute myeloid leukemia, pancreatic cancer, and colorectal cancer." (PMID 39013578, 2024).
gastric cancer (12 papers, 2015 to 2024). A primary or metastatic malignant neoplasm involving the stomach. "ZNF471 acts as a tumor suppressor in gastric cancer by transcriptionally inhibiting downstream targets TFAP2A and PLS3." (PMID 33133131, 2020). "In conclusion, ZNF471 acts as a tumor suppressor in gastric cancer by transcriptionally inhibiting downstream targets TFAP2A and PLS3." (PMID 29610526, 2018). "Taken together, KAP1 serves as a co-repressor for ZNF471 in gastric cancer, inducing elevated H3K9me3 in the promoter of TFAP2A and PLS3." (PMID 29610526, 2018). "Combining the EMSA result and GSEA with TCGA Stomach Cancer gene expression RNAseq data, we identified TFAP2A and PLS3, as the critical targets of ZNF471." (PMID 29610526, 2018). "We also showed that EGCG inhibited cell proliferation and reversing the 5-FU resistance of gastric cancer through inactivation of TFAP2A/VEGF signaling pathway." (PMID 29137307, 2017). "All in a word, our datas have revealed that EGCG inhibits GC growth and reversal of fluorouracil resistance of gastric cancer cells through inactivation of TFAP2A/VEGF signaling pathway and down-regulation of MDR-1 and P-gp expression." (PMID 29137307, 2017). "Specifically, five transcription factors MYB, MYBL2, ETV4, LEF1 and TFAP2A were up-regulated and they formed the TF-gene regulatory networks with 41 genes, 38 of which were up-regulated and 3 were down-regulated in gastric cancer tissues." (PMID 25860484, 2015). "Hence, ZNF471 suppressed gastric cancer progression by transcriptionally repressing its downstream targets TFAP2A and PLS3 in co-operating with KAP1." (PMID 29610526, 2018). "Transcription factors MYB, MYBL2, ETV4, LEF1,TFAP2A were up-regulated in gastric cancer tissues." (PMID 25860484, 2015). "ZNF471 suppresses gastric cancer by transcriptionally repressing the PLS3 and TFAP2A downstream oncogenes." (PMID 39695171, 2024). "The zinc-finger protein 471 was shown to inhibit gastric cancer progression through transcriptionally repressing downstream PLS3 and TFAP2A, suggesting that TFAP2A and PLS3 act as oncogenic factors in gastric cancer cell development." (PMID 36707053, 2023). "Taken the EMSA and GSEA results together, we therefore focused on the functional role of TFAP2A and PLS3 in gastric cancer." (PMID 29610526, 2018). "We demonstrated the oncogenic properties of TFAP2A in promoting cell proliferation, migration and invasion and PLS3 in inducing cell migration and invasion in gastric cancer cell lines." (PMID 29610526, 2018). "We detected the inhibition of gastric cancer cell proliferation by EGCG, and which related to its regulatory action on VEGF expression, secretion and TFAP2A expression." (PMID 29137307, 2017). "Similarly, EGCG reduces the expression of MDR1 and P-gp through the TFAP2A/VEGF pathway, thus restoring the sensitivity of gastric cancer cells to 5-fluorouracil (5-FU)." (PMID 34113488, 2021). "Enhanced gastric cancer cell colony formation ability due to ZNF471 knockdown by shRNA was abolished through further knocking down of TFAP2A, indicating that the tumor-suppressive effect of ZNF471 is partially dependent on TFAP2A suppression." (PMID 29610526, 2018). "TFAP2A and PLS3 showed oncogenic functions in gastric cancer cell lines." (PMID 29610526, 2018). "However, consistent with the decreased VEGF secretion from gastric cell, phosphorylation of TFAP2A was also significantly decreased in 5-Fluorouracil resistant cells for treatment with EGCG in the parental and resistant gastric cancer cells." (PMID 29137307, 2017). "However, our results shown that phosphorylation of TFAP2A was obviously surppressed in 5-Fluorouracil resistant cells by EGCG treatment, suggested that activation of TFAP2A/VEGF pathway seems to be one of the molecular mechanisms which was produced during gastric cancer cells resistance acquisition." (PMID 29137307, 2017).
microphthalmia (9 papers, 2010 to 2022). Congenital or developmental anomaly in which the eyeballs are abnormally small. "Dominant mutations in TFAP2A are associated with syndromic anophthalmia/microphthalmia and other ocular phenotypes as part of Branchio-Ocular-Facial-Syndrome (BOFS)." (PMID 27609212, 2016). "This is highlighted by the human Branchio-Oculo-Facial Syndrome, which is associated with TFAP2A mutations and is characterized by craniofacial (cleft lip, cleft palate, ear malformations) and ocular anomalies (anophthalmia, microphthalmia, cataract, and coloboma)." (PMID 33182738, 2020). "Like humans, Tfap2a zebrafish and mouse mutants display microphthalmia and coloboma, indicating that neural crest-specific expression has cell non-autonomous effects on the optic cup." (PMID 33182738, 2020). "Upregulated expression of TFAP2A in fiber cells resulted in microphthalmia and cataracts in transgenic mice but blocked fiber cell differentiation." (PMID 33006594, 2020). "Consistent with this, the case 3 showed microphthalmia with corneal clouding and it was the only case carried deletion of the region R9 including the TFAP2A gene." (PMID 26174853, 2015).
pancreatic cancer (9 papers, 2009 to 2025). "We found that TFAP2A expressions were significantly elevated in pancreatic cancer tissues and were associated with poor prognostic outcomes." (PMID 35494004, 2022). "A recent study about pancreatic cancer showed that solasonine is directly bound to TFAP2A and suppressed its protein levels." (PMID 38265973, 2024). "Indirectly, it is observed in progressive pancreatic cancer, and TFAP2A can bind the promotor region of OTU Deubiquitinase (OTUB1) to upregulate its expression." (PMID 37291585, 2023). "For example, miR-200a targets TFAP2C mRNA, miR-200b suppresses TFAP2A expression in cholangiocarcinoma, miR-3960 suppresses TFAP2A mRNA in the pancreatic cancer, and miR-27a inhibits TFAP2B mRNA in HCC." (PMID 37291585, 2023). "To clarify the mechanism of TFAP2A in pancreatic cancer, we first analyzed the TCGA and GTEx databases and compared the expressions as well as survival differences of TFAP2A in tumors (n=179) and normal tissues (n=171)." (PMID 35494004, 2022). "In vitro, overexpressed TFAP2A enhanced pancreatic cancer cell proliferation, suppressed their apoptosis, and promoted the expressions of downstream OTUB1." (PMID 35494004, 2022). "The area under ROC curve of the TCGA cohort was 0.976 in TFAP2A, implying a highly accurate predictive power of TFAP2A in pancreatic cancer." (PMID 35494004, 2022). "The mRNA levels of TFAP2A in pancreatic cancer tissues were significantly upregulated, compared to normal tissues." (PMID 35494004, 2022). "For example, overexpressed TFAP2A could increase the sensitivity to gemcitabine in pancreatic cancer and increase chemosensitivity to adriamycin and cisplatin in lung carcinoma." (PMID 37291585, 2023). "In summary, solasonine inhibits the TFAP2A/OTUB1/SLC7A11 axis to stimulate ferroptosis and prevent the spread of pancreatic cancer cells." (PMID 40070365, 2025). "In summary, solasonine inhibits the TFAP2A/OTUB1 SLC7A11 axis to activate ferroptosis and suppress pancreatic cancer cell progression." (PMID 35494004, 2022). "In conclusion, solasonine is involved in ferroptosis by suppressing TFAP2A-mediated transcriptional upregulation of OTUB1, thereby activating ubiquitinated degradation of SLC7A11 and promoting pancreatic cancer cell ferroptosis." (PMID 35494004, 2022).
nasopharyngeal carcinoma (8 papers, 2015 to 2023). A carcinoma arising from the nasopharyngeal epithelium. "Previous work on nasopharyngeal carcinoma also reported the involvement of TFAP2A in the early occurrence of SCC21." (PMID 36914617, 2023). "For example, TFAP2A is overexpressed in human nasopharyngeal carcinoma and promotes tumorigenesis by influencing the HIF-1α/VEGF/PEDF pathway." (PMID 33713277, 2021). "It was reported that TFAP2A had oncogenic roles in other cancer types of head and neck, breast and nasopharyngeal carcinoma." (PMID 29610526, 2018). "For example, TFAP2A expression was elevated in nasopharyngeal carcinoma, which promoted nasopharyngeal carcinoma proliferation and growth via inducing cyclooxygenase-2 expression; in addition, TFAP2B was reported to be overexpressed in non-small cell lung cancer (NSCLC) tissues and cell lines." (PMID 29439714, 2018). "In nasopharyngeal carcinoma, TFAP2A regulated tumor cell growth and survival through the HIF-1α-mediated VEGF/PEDF signaling pathway, suggesting that TFAP2A could be a potential biomarker for nasopharyngeal carcinoma treatment." (PMID 25860484, 2015). "For instance, TFAP2A, an identified cofactor not found in any of the major databases, was demonstrated to interact with HIF1A to target the VEGF pathway in nasopharyngeal carcinoma cells." (PMID 36347941, 2022).
coloboma (7 papers, 2010 to 2024). An abnormality in which a part of a structure in one or both eyes is missing. "Of the 38 known coloboma‐associated genes, the analysis identified novel variants in two genes, CHD7, TFAP2A, and previously reported variants in RARB and BMP7, in a total of four unrelated families." (PMID 31816153, 2020). "We identified novel variants in genes such as TFAP2A and CHD7, and previously reported variants in RARB and BMP7, indicating that mutations in known coloboma‐associated genes account for only 4.5% of the coloboma cohort analyzed." (PMID 31816153, 2020). "Abrogation of genes encoding transcription factors implicated in POM development, such as zic2, lmx1b, and TFAP2A/tfap2a leads to lack of apposition of the ventral retinal lips and coloboma." (PMID 29515375, 2018).